GPR88 (G protein-coupled receptor 88)
Diseases named in the same sentence as GPR88 in open-access papers:
GPR88 is named in the same sentence as 26 diseases in open-access papers, as found by Europe PMC text mining. Sharing a sentence is not in itself a finding about the gene and the disease. The quoted sentences say what the papers report.
Anxiety (9 papers, 2016 to 2025). Intense feelings of nervousness, tension, or panic often arise in response to interpersonal stresses. "A recent study also linked GPR88 to anxiety disorders, as the GPR88-knockout mice exhibited low anxiety compared to wild-type animals." (PMID 28347302, 2017). "GPR88, a striatal enriched orphan G-protein-coupled receptor has been implicated in the regulation of anxiety-like behaviors." (PMID 27570825, 2016). "While GPR88 in D2R-MSNs regulates levels of anxiety, social behavior, stereotypies, locomotion, and motor coordination, this receptor in D1R-MSNs does not seem to impact affective behaviors but regulates habituation to novelty and motor skill learning." (PMID 31346000, 2019). "The deletion of Gpr88 specifically in D2R-neurons is sufficient to decrease anxiety-like behaviors and increase social approach." (PMID 31346000, 2019). "In sum, data from marble burying and social interaction tests reveal a D2R cell-specific function of GPR88 in anxiety-related and social behavior, as modifications are detected in CMV-Gpr88 and A2AR-Gpr88 KO, but not D1R-Gpr88 KO, mice." (PMID 31346000, 2019). "The total deletion of Gpr88 in mice was shown to decrease anxiety-like behaviors, increase stereotypies and locomotion, and impair motor coordination and motor learning." (PMID 31346000, 2019). "The total Gpr88 gene deletion in mice also induced failure to habituate to an open field or automated home-cage environment and decreased anxiety-like behaviors." (PMID 31346000, 2019). "Recently, we found that Gpr88 deletion in mice also decreases anxiety-like behavior, implicating this receptor in emotional processing and in the evaluation of environmental stimuli value." (PMID 27570825, 2016). "To further investigate the role of GPR88 in approach–avoidance conflict-based anxiety tests, we measured avoidance and approach behaviors separately in both mouse lines." (PMID 27570825, 2016). "Together, these data show that the GPR88 deletion in A2AR neurons fully accounts for the high levels of anxiety observed in total GPR88 KO mice in this study and our previous study." (PMID 27570825, 2016). "Complete deletion of Gpr88 in mice decreased anxiety levels in several models of anxiety-like behavior." (PMID 27570825, 2016). "Here, we investigated whether deletion of Gpr88 in D1R-neurons also modifies anxiety-related and/or social behaviors." (PMID 31346000, 2019). "In a previous report, we showed that Gpr88−/− mice present decreased anxiety-like behaviors." (PMID 27570825, 2016). "To examine whether this behavior is dependent on GPR88 in A2AR neurons, we evaluated anxiety-like behaviors of Gpr88A2A-Cre and Gpr88−/− mice in the standard light/dark and elevated plus maze test." (PMID 27570825, 2016). "Finally, further demonstration of GPR88 implication in anxiety-related behaviors and threat evaluation definitely posit GPR88 blockade as a new target for the treatment of anxiety-related disorders." (PMID 27570825, 2016). "GPR88, known for its role in modulating anxiety, may therefore influence stress‐induced reinstatement through its effects on neural circuits involved in both anxiety and reward processing." (PMID 40536830, 2025). "Importantly, the loss of one copy of Gpr88 did not affect anxiety- or depressive-like behaviors displayed in the elevated plus-maze test, open field test, marble-burying test or tail suspension test." (PMID 35755440, 2022). "We observe significant enrichment of NTSR2, GPR88 and Gabrg1 in chloroquine-activated neurons, and relatively lower expression of OPRM1, PENK and Chrm1, suggesting that these genes could be critical candidates in regulating pruritis and its associated anxiety." (PMID 34032210, 2021). "Time of day, however, was a major factor in the regulation of anxiety-like behavior assessed in the EPM and OFT in Gpr88(cre/+) and Gpr88(+/+) male and female mice, suggesting daily variations in those behaviors." (PMID 35755440, 2022).
Anxiety (continued). "To evaluate the contribution of GPR88 in D2R MSNs, we compared behavioral responses of A2AR-Gpr88 KO mice with those of total Gpr88 KO animals using behavioral tests measuring anxiety-like behaviors and fear responses." (PMID 27570825, 2016). "To evaluate the contribution of GPR88 in D2R-neurons, we compared anxiety-like and fear-related behavioral responses of newly generated conditional A2AR-Gpr88 mice with those of total Gpr88 knock-out animals." (PMID 27570825, 2016). "In sum, our analysis of Gpr88A2A-Cre mice shows that GPR88 in A2AR MSNs regulates locomotor and anxiety behaviors." (PMID 27570825, 2016). "We find that specific deletion of Gpr88 in D2R-MSNs, but not in D1R-MSNs, decreases anxiety-like behavior as shown by reduced defensive burying activity." (PMID 31346000, 2019). "We show that Gpr88 expressed in these neurons is responsible for ethological anxiety-like behaviors, but does not regulate conflict anxiety and fear responses." (PMID 27570825, 2016). "This strongly suggests that GPR88 in D2R neurons, but not in D1R neurons, regulate anxiety-like behaviors; however, we cannot exclude that GPR88 also regulates emotional behavior in A2AR-expressing neurons at extrastriatal sites." (PMID 27570825, 2016). "In the present study, we show that GPR88 in A2AR-expressing neurons regulates anxiety-like behaviors without affecting fear conditioning and drive toward novelty or food." (PMID 27570825, 2016). "We conclude that Gpr88 expressed in A2AR neurons enhances ethological anxiety-like behaviors without affecting conflict anxiety and fear responses." (PMID 27570825, 2016). "Our data show that GPR88 expressed in A2AR neurons increases ethological anxiety-like behaviors without affecting conflict anxiety and fear responses." (PMID 27570825, 2016). "A conditional KO mouse line for GPR88 in D2R-MSNs was developed in a previous study, using a A2AR-Cre driver line (A2AR-Gpr88 mice), and mutant mice showed hyperactive behavior, decreased anxiety-like behaviors and increased locomotor response to dopaminergic agonists." (PMID 31346000, 2019). "As such, the low-anxiety phenotype of mice lacking GPR88 could result from increased drive toward novelty exploration, decreased avoidance of a threatening environment, or both factors." (PMID 27570825, 2016). "To determine whether GPR88 in D2R-expressing neurons contributes to this emotional phenotype, we generated conditional Gpr88 knock-out mice using adenosine A2AR (A2AR)-Cre-driven recombination, and compared anxiety-related responses in both total and A2AR-Gpr88 KO mice." (PMID 27570825, 2016).
schizophrenia (7 papers, 2014 to 2024). A major psychotic disorder characterized by abnormalities in the perception or expression of reality. "Human gene association studies show a rising correlation between GPR88 function and mental health issues, including schizophrenia and bipolar disorder as well as neurodevelopmental and neurodegenerative disease." (PMID 36187336, 2022). "GPR88 has been discovered as a genetic risk factor for bipolar illness and schizophrenia by genetic association analysis." (PMID 36187336, 2022). "GPR88 knockout mice show abnormal behaviors associated with schizophrenia, such as disrupted sensorimotor gating, accentuated behavioral response to apomorphine and amphetamine, and impaired learning." (PMID 26101869, 2015). "Previous studies have identified GPR88 as a susceptibility gene for both bipolar disorder and schizophrenia by a genetic association analysis, and antidepressant treatment increases GPR88 expression." (PMID 26101869, 2015). "GPR-88 expression was directly associated with schizophrenia in a group study in South Africa." (PMID 38256919, 2024). "For example, a study with the orphan receptor GPR88 used molecular and behavioral tests to propose a role for this receptor in schizophrenia." (PMID 26005419, 2015). "From the currently available studies regarding the potential association between GPR expression and schizophrenia, we identified twelve studies out of which two were on GPR-52 expression, four on GPR-85 expression, four on GPR-88 expression, and one on GPR-139 expression." (PMID 38256919, 2024).
bipolar disorder (4 papers, 2014 to 2024). A disorder of the brain that causes unusual shifts in mood, energy, activity levels and the ability to carry out day-to-day tasks. "GPR88, coding for a G protein-coupled orphan receptor that is highly represented in the striatum, is a strong functional candidate gene for neuropsychiatric disorders and is located at 1p22-p21, a chromosomal region that we have previously linked to bipolar disorder (BD) in the Sardinian population." (PMID 24689078, 2014).
Chorea (4 papers, 2020 to 2024). Chorea (Greek for 'dance') refers to widespread arrhythmic involuntary movements of a forcible, jerky and restless fashion. "A homozygous non-sense variant affecting the GPR88 gene has been reported in four sisters of a single family with childhood-onset chorea and psychomotor retardation." (PMID 36003298, 2022). "While direct links between Gpr88 mutations and human PD are lacking, sporadic chorea cases in humans have been associated with mutations in GPR88." (PMID 38895631, 2024).
Parkinson disease (3 papers, 2020 to 2026). A progressive degenerative disorder of the central nervous system characterized by loss of dopamine producing neurons in the substantia nigra and the presence of Lewy bodies in the substantia nigra and locus coeruleus. "Consequently, GPR88 is emerging as a potential drug target for the treatment of various human central nervous system (CNS) related diseases, including schizophrenia, Parkinson’s disease (PD), bipolar disorder, anxiety, depression, and addiction." (PMID 35501348, 2022). "Here, we highlighted the role of 3 genes (GPR88, GPNMB, and GMPR) showing higher expression in CM (FC > 4) and that could be interesting key players of CM since higher expression of them are also associated to Parkinson's and Alzheimer's diseases." (PMID 32801995, 2020). "GPR88 is an orphan receptor highly expressed in the striatum where it modulates dopamine and thus is a potential target for neuropsychiatric disorders such as ADHD, substance abuse, and Parkinson’s disease." (PMID 41330618, 2026).
depression (2 papers, 2022 to 2025). "Structural and functional abnormalities in the striatum are well-documented in depression; altered GPR88 expression has been linked to learning deficits and neuropsychiatric disorders." (PMID 39858610, 2025). "Although, it has been shown that GPR88 mRNA levels are changed with antidepressant treatment further behavioral studies are needed to evaluate the effect of GPR88 on depression-like behavior." (PMID 33589739, 2022).
Dyskinesia (2 papers, 2019 to 2024). A movement disorder which consists of effects including diminished voluntary movements and the presence of involuntary movements. "GPR88 proteins seem to be promising targets for the mitigation of dyskinesia." (PMID 38895631, 2024). "For instance, Gpr88 knockdown seem to prevent the onset of dyskinesia." (PMID 38895631, 2024). "This will allow for dissecting more precisely the role of Gpr88 and for developing gene therapy tools that may offer alternative and possibly more efficient solutions than pharmacological interventions for treating the motor dysfunction of PD while avoiding the eventual emergence of dyskinesia." (PMID 31708775, 2019). "Thus, to evaluate Gpr88 as a potential target for the management of PD and L-DOPA–induced dyskinesia (LID), we inactivated Gpr88 by lentiviral-mediated knock-down with a specifically designed microRNA (miR) (KD-Gpr88) in a 6-OHDA rat model of hemiparkinsonism." (PMID 31708775, 2019).
Intellectual disability (2 papers, 2020 to 2024). "The GTEx expression as well as KEGG Pathway both indicate that GPR88 is highly related to intellectual disability, as GPR88 has extremely high expression among brain tissues compared to the other tissues and other genes that are overexpressed in brain tissues." (PMID 32858868, 2020). "This suggests one potential connection between GPR88 and intellectual disability." (PMID 32858868, 2020).
ischaemic stroke (2 papers, 2015 to 2021). "Previously, we identified the human orthologues for a number of rat genes, which expression was changed after ischaemic stroke (Adora2a, Bcl3, Ccl22, Ccr1, Cd14, Gpr6, Gpr88, Rgs9, and other genes)." (PMID 34946819, 2021). "Among the downregulated genes, Gpr88, Rgs9, Enthd1, Olr59, P2ry12, Degs2, Pde10a, Neu2, Adora2a, and Slc22a6 were found to demonstrate significant downregulation in pathological phase of ischemic stroke." (PMID 25861363, 2015).
Obesity (2 papers, 2017 to 2022). Accumulation of substantial excess body fat. "Our data showed that VMH AAV GPR88* mice exhibited increased susceptibility to obesity under either SCD or HFD feeding conditions and that the phenotype was more severe than those of VMH AC3 KD and VMH pIFT88‐AC3 KD mice." (PMID 34783461, 2022). "Effects of high fat diets on the manifestation of GPR88 deficiency were also addressed in comparison with standard chow feeds to examine the potential influence of Gpr88 deletion on diet-induced obesity." (PMID 28855710, 2017). "In other words, stimulation of GPR88 signalling is conjectured to trigger hyperphagia and increase susceptibility to obesity, whereas such obesogenic drive may be counteracted by feedback regulatory mechanisms efficiently to boost metabolism and prevent excessive adipose deposition." (PMID 28855710, 2017). "The obesity phenotype of VMH AAV GPR88* mice was comparable to that of mice in which GPR88* is exogenously expressed in Sim1‐expressing neurons within the PVN region." (PMID 34783461, 2022). "Taken together, these results indicated that VMH AAV GPR88* mice are subject to obesity accompanied by lower energy expenditure." (PMID 34783461, 2022). "Future research elucidating the pharmacology and neurochemical dynamics of GPR88 will shed light on the therapeutic potential of this orphan receptor in obesity treatment." (PMID 28855710, 2017). "Under conditions of diet-induced obesity, Gpr88 ablation improved body lean content, weight recovery and feeding following fasting, insulin responsiveness and glucose tolerance." (PMID 28855710, 2017). "Thus, we feel that care should be taken in the attribution of the obesity phenotypes induced by exogenous GPR88* expression in MC4R‐expressing neurons of the PVN to the inhibition of ciliary AC3 expression." (PMID 34783461, 2022). "The augmented drop in adiposity in Gpr88−/− mice on HFD than chow suggested that GPR88 may function as part of the biological defense of elevated body fat during obesity development." (PMID 28855710, 2017). "Findings from this study suggest that targeting GPR88 could have beneficial effects in modulating fat accretion, feeding behavior, and glucose homeostasis in obesity-related comorbidities." (PMID 28855710, 2017). "Considering the results together, we concluded that the VMH pIFT88‐AC3 KD mice exhibited more severe HFD‐induced obesity than the controls, although their obesity phenotypes were not as pronounced as those of the VMH AAV GPR88* mice." (PMID 34783461, 2022).
alcohol use disorder (1 paper, 2025). "GPR88, an orphan G protein‐coupled receptor primarily expressed in the striatum, has emerged as a potential target for treating alcohol use disorder (AUD) due to its role in modulating reward and motivational pathways." (PMID 40536830, 2025).
developmental delay (1 paper, 2020). "Indeed, according to previous studies, GPR88 deficiency in humans is theorized to manifest as developmental delay with pronounced speech acquisition impairment, learning disabilities, and hyperkinetic movement disorder at 8–9 years of age." (PMID 32858868, 2020).
internalizing disorder (1 paper, 2025). A type of mental or behavioral disorder, typically in children and young adults, with symptoms including depression, anxiety and withdrawal. "Among the implicated genes, G protein-coupled receptor 88 (GPR88), primarily expressed in the striatum, may influence susceptibility to internalizing disorders through its role in motivation and reward processing, pathways often disrupted in depressive states." (PMID 39858610, 2025).
itch (1 paper, 2021). "We observed considerable overlap between NTSR2+ve (75.31% cells), GPR88+ve (69.35%) and Gabrg1+ve (62.32% cells) cells with itch-activated Fos+ve cells in the CeA." (PMID 34032210, 2021).
mental disorder (1 paper, 2017). A disease that has its basis in the disruption of mental process. "Several other essential genes (Gpr88 and Edn1) involved in mental disorder, learning, and memory were also suppressed in the hippocampus of Utx cKO mice." (PMID 28970783, 2017).
psychiatric disorder (6 papers, 2014 to 2024). A disorder characterized by behavioral and/or psychological abnormalities, often accompanied by physical symptoms. "A large amount of studies implicate a priori Gpr88 in the pathophysiology of psychiatric diseases." (PMID 24689078, 2014). "Furthermore, GPR88 expression has been previously shown to be altered after administration of mood stabilizers, antidepressants, and drugs related to treatment of addiction which highlights its relevance for the treatment of psychiatric disorders." (PMID 39334510, 2024).
nervous system diseases (1 paper, 2021). "In the present study, we found that some genes of benefit to nervous system disease were activated (such as Lhx8, GPR88, RGS9, CD4, DRD2, RXRG, and Syt6), following the increase in the number of cholinergic and GABAergic neurons in the HSHF-diet offspring." (PMID 33819195, 2021). "As the offspring became older (16 months of age), we found that some genes of benefit to nervous system disease were activated, such as Lhx8, GPR88, RGS9, CD4, DRD2, RXRG, and Syt6, following the increase in the number of cholinergic and GABAergic neurons." (PMID 33819195, 2021). "The mRNAs of Rgs9, Gpr88, Drd2, Sh3rf2, Tac1, Serpina 9, Rxrg, Drd1, Rasgrp2, Six3, Gpr6, Pdyn, Gng7, and Pde1b were all upregulated (p < 0.05); all of these have been reported to be more or less related to nervous system diseases." (PMID 33819195, 2021). "When the offspring grew older (16 months), we found that some genes of benefit against nervous system disease were activated, such as Lhx8, GPR88, RGS9, CD4, DRD2, RXRG, and Syt6, and the expression of cholinergic and GABAergic neurons biomarker protein increased." (PMID 33819195, 2021).
GPR88 also shares sentences with these, for which no sentence is quoted: alcohol (1 paper); Alzheimer disease (1); anxiety disorder (1); Dystonia (1); Hypertension (1); learning disabilities (1); Parkinson's (1); psychosis (1); substance abuse (1).